VSIG4 (V-set and immunoglobulin domain containing 4)
Diseases named in the same sentence as VSIG4 in open-access papers (continued):
Sharing a sentence is not in itself a finding about the gene and the disease.
infection (8 papers, 2017 to 2025). The state of being infected such as from the introduction of a foreign agent such as serum, vaccine, antigenic substance or organism. "Parallel evaluations of body weight changes over the course of infection suggested that the control mice experienced less severe disease than did the VSIG4 gene-deficient mice." (PMID 41150440, 2025). "The growing body of evidence supporting the protective functions of VSIG4 across various infectious contexts not only enhances our understanding of its underlying mechanisms but also highlights the importance of considering immune homeostasis in the development of therapies for severe infections." (PMID 41150440, 2025). "To further investigate the mechanism of VSIG4-mediated protection from influenza virus infection, we evaluated the immune responses against infection." (PMID 41150440, 2025). "Noticeably, Vsig4−/− mice died rapidly following MHV-3 infection in contrast to WT littermates (log-rank test, p = 0.0339)." (PMID 29109438, 2017). "We observed that the VSIG4-deficient mice succumbed to sublethal infection, regardless of the influenza virus strain used." (PMID 41150440, 2025). "Next, we used a VSIG4-neutralized antibody to further explore whether VSIG4 downregulation could decrease the expression of TGF-β in dMφ after infection." (PMID 38730500, 2024). "Finally, Vsig4−/− mice responded with severe fibrinogen formation, leading to increased liver coagulation and necrosis post infection." (PMID 29109438, 2017).
kidney diseases (4 papers, 2020 to 2024). "However, the role of VSIG4 in kidney diseases has been scarcely reported, and the reported results are conflicting." (PMID 36836636, 2023). "A few studies have analyzed the role of VSIG4 in kidney disease models." (PMID 36836636, 2023). "These previous and present study findings suggest that VSIG4 might play a role in the fibrotic progression of kidney diseases." (PMID 36836636, 2023). "Further studies are required to clarify the role of VSIG4 in kidney diseases." (PMID 36836636, 2023). "Limited studies have shown the role of VSIG4 in kidney diseases." (PMID 35888119, 2022). "Importantly, this smartphone-based analyzing and reporting system allows for discriminating LN patients with active renal disease from healthy controls with the area-under-the-curve (AUC) value = 0.9 for TNFRSF1b and 1.0 for VSIG4, respectively, indicating high predictive accuracy." (PMID 38534254, 2024). "However, the role of VSIG4 in kidney diseases is still unclear." (PMID 36836636, 2023).
bacterial infection (2 papers, 2021 to 2025). "Thus, to assess whether the loss of MΦres functional markers (i.e. Tim4, CD73, Vsig4) was due to the elicited inflammatory response, we analysed peritoneal exudate cells from animals subjected to prolonged bacterial infection." (PMID 34386014, 2021).
inflammation (1 paper, 2023). Aberrant reaction of the microcirculation characterized by movement of fluid and leukocytes from the blood into extravascular tissues. "Gut mEV treatment resulted in cardiac inflammation and a reduction in cardiac contractility in young Vsig4-/- mice." (PMID 37520546, 2023).
VSIG4 also shares sentences with these, for which no sentence is quoted: atherosclerosis (5 papers); cardiovascular disease (3); alcohol (2); Autoimmunity (2); benign ovarian tumors (2); infectious disease (2); liver (2); non-small cell lung carcinoma (2); acute myocardial infarction (1); alcoholic hepatitis (1); Alzheimer disease (1); autoimmune type 1 diabetes (1); cardiac interstitial fibrosis (1); central nervous system lymphomas (1); chronic obstructive pulmonary disease (1); Cirrhosis (1); diffuse large B-cell lymphoma (1); fibrosarcoma (1); fungal infection (1); glaucoma (1); Glucose intolerance (1); hemophagocytic lymphohistiocytosis (1); high-grade glioma (1); immune deficiency (1); infarction (1); ischemia (1); leprosy (1); liver diseases (1); melanoma (1); mesothelioma (1).
A further 11 diseases each share a sentence with VSIG4 in 1 paper.